ISG15 (ISG15 ubiquitin like modifier)
Description:
Ubiquitin-like protein which plays a key role in the innate immune response to viral infection either via its conjugation to a target protein (ISGylation) or via its action as a free or unconjugated protein. ISGylation involves a cascade of enzymatic reactions involving E1, E2, and E3 enzymes which catalyze the conjugation of ISG15 to a lysine residue in the target protein. Its target proteins include IFIT1, MX1/MxA, PPM1B, UBE2L6, UBA7, CHMP5, CHMP2A, CHMP4B and CHMP6. Isgylation of the viral sensor IFIH1/MDA5 promotes IFIH1/MDA5 oligomerization and triggers activation of innate immunity against a range of viruses, including coronaviruses, flaviviruses and picornaviruses. Can also isgylate: EIF2AK2/PKR which results in its activation, RIGI which inhibits its function in antiviral signaling response, EIF4E2 which enhances its cap structure-binding activity and translation-inhibition activity, UBE2N and UBE2E1 which negatively regulates their activity, IRF3 which inhibits its ubiquitination and degradation and FLNB which prevents its ability to interact with the upstream activators of the JNK cascade thereby inhibiting IFNA-induced JNK signaling. Exhibits antiviral activity towards both DNA and RNA viruses, including influenza A, HIV-1 and Ebola virus. Restricts HIV-1 and ebola virus via disruption of viral budding. Inhibits the ubiquitination of HIV-1 Gag and host TSG101 and disrupts their interaction, thereby preventing assembly and release of virions from infected cells. Inhibits Ebola virus budding mediated by the VP40 protein by disrupting ubiquitin ligase activity of NEDD4 and its ability to ubiquitinate VP40. ISGylates influenza A virus NS1 protein which causes a loss of function of the protein and the inhibition of virus replication. The secreted form of ISG15 can: induce natural killer cell proliferation, act as a chemotactic factor for neutrophils and act as a IFN-gamma-inducing cytokine playing an essential role in antimycobacterial immunity. The secreted form acts through the integrin ITGAL/ITGB2 receptor to initiate activation of SRC family tyrosine kinases including LYN, HCK and FGR which leads to secretion of IFNG and IL10; the interaction is mediated by ITGAL.
Synonyms: IP17; hUCRP; G1P2; UCRP; IFI15; IMD38
Tractability: Small molecule: a structure with a bound ligand is known. Antibody: UniProt places it where antibodies can reach, with high confidence; its Gene Ontology location is reachable by antibodies, with high confidence. PROTAC: ubiquitination databases record sites on it; its protein half-life has been measured.
Gene: Protein-coding gene on chromosome 1 (1,001,138 to 1,014,540, forward strand). Ensembl gene ENSG00000187608.
Subcellular location: Cytoplasm; Secreted
Pathways (Reactome):
Immune System: DDX58/IFIH1-mediated induction of interferon-alpha/beta; ISG15 antiviral mechanism; Interferon alpha/beta signaling; Modulation of host responses by IFN-stimulated genes; Negative regulators of DDX58/IFIH1 signaling; PKR-mediated signaling
Disease: NS1 Mediated Effects on Host Pathways; RSV-host interactions; SARS-CoV-2 activates/modulates innate and adaptive immune responses
DNA Repair: Termination of translesion DNA synthesis
Gene Ontology:
Molecular function: integrin binding; protein binding; protein tag activity
Biological process: defense response to bacterium; defense response to virus; innate immune response; integrin-mediated signaling pathway; ISG15-protein conjugation; negative regulation of protein ubiquitination; negative regulation of type I interferon-mediated signaling pathway; negative regulation of viral genome replication; positive regulation of interferon-beta production; positive regulation of interleukin-10 production; positive regulation of protein oligomerization; positive regulation of type II interferon production; protein localization to mitochondrion; regulation of type II interferon production; response to type I interferon; response to virus; modification-dependent protein catabolic process; positive regulation of bone mineralization; positive regulation of erythrocyte differentiation; positive regulation of multicellular organismal process; regulation of immune system process
Cellular component: cytoplasm; extracellular region; cytosol; cytosolic ribosome; nucleoplasm; nucleus
Genetic constraint (gnomAD): Loss-of-function variants: 2 observed, 2.61 expected, observed/expected ratio (o/e) 0.77, 90% interval 0.3 to 1.8. That is too few expected variants to judge how well the gene tolerates losing a copy. Missense variants: 224 observed, 238.38 expected, observed/expected ratio (o/e) 0.94, 90% interval 0.84 to 1.05. Synonymous variants: 116 observed, 112 expected, observed/expected ratio (o/e) 1.04, 90% interval 0.89 to 1.21.
Homologues: Orthologues: chimpanzee ISG15 (98% identical), macaque ISG15 (91% identical), dog ISG15 (69% identical), pig ISG15 (66% identical), rabbit ISG15 (65% identical), mouse Isg15 (62% identical), rat Isg15 (60% identical), guinea pig ISG15 (57% identical), zebrafish isg15 (33% identical). Paralogues in human: UBL4A (20% identical), UBL4B (19% identical), ZFAND4 (18% identical), RPS27A (17% identical), UBC (16% identical), UBA52 (16% identical), ANKUB1 (15% identical), UBD (15% identical), NEDD8 (12% identical), UBB (3% identical).
Diseases named in the same sentence as ISG15 in open-access papers:
ISG15 is named in the same sentence as 289 diseases in open-access papers, as found by Europe PMC text mining. Sharing a sentence is not in itself a finding about the gene and the disease. The quoted sentences say what the papers report.
viral infection (312 papers, 2008 to 2026). "We and others have previously shown that pretreatment of ISG15‐deficient cells with IFN‐α renders them resistant to viral infection." (PMID 39931755, 2025). "For example ISG15-deficient patients have been found to be more susceptible to mycobacterial infections; however, they display increased resistance to viral infections on account of sustained IFN signalling and presence of ISGs." (PMID 36416643, 2022). "Previous reports have indicated that IFNα treatment of ISG15-deficient patient cells exhibited increased resistance to several viral infection." (PMID 36315588, 2022). "The results of this study align with previous results demonstrating that ISG15 deficiency restricts different viral infections." (PMID 35333911, 2022). "Humans with complete ISG15 deficiency express persistently elevated levels of ISGs, and consequently, exhibit broad spectrum resistance to viral infection." (PMID 35333911, 2022). "Although the ISG15 protein was discovered in 1979, its nature and function were not elucidated for many years, until researchers discovered that IFN-induced ISG15 and its covalent form were implicated as a central player in the process of viral infection." (PMID 34901029, 2021). "The cellular effects caused by protein ISGylation depends on the stage of viral infection and what specific substrate proteins are being targeted by the ISG15 cascade." (PMID 34207696, 2021). "Conjugation of ISG15 to viral proteins results in their loss of function and the evolutionary importance of this pathway in controlling viral infection is demonstrated by the emerging number of viral proteins that have evolved to disrupt this pathway." (PMID 31396205, 2019). "In general, ISG15 is involved in anti-viral pathways and ISG15-deficient mice are highly susceptible for viral infections like herpes or influenza." (PMID 29186924, 2017). "We find that, not only do humans deficient in ISG15 lack any overt susceptibility to viral infection, but cells derived from these individuals exhibit an enhancement of broad protection against viruses." (PMID 27193971, 2016). "A function of ISG15 in this process would also at least partially explain the high susceptibility of ISG15−/− mice to viral infections." (PMID 24137104, 2013). "Interferon- Stimulated Gene 15 (ISG15), encoding an ubiquitin-like protein, is significantly induced by type I interferons or viral infections." (PMID 21992229, 2011). "While some other work indicate that Isg15-/- or Ube1L-/- (ISG15 E1) mice are more susceptible to many viral infections, such as influenza A/B, herpes simplex virus and SNV, than WT mice." (PMID 21992229, 2011). "Mice deficient of ISG15 have been shown to be more susceptible to influenza, herpes, and Sindbis viruses' infection." (PMID 20569475, 2010). "ISG15 has also been found to drive antiviral immune functions by modifying viral proteins, inhibiting viral replication, and regulating host signaling pathways associated with viral infection." (PMID 37007947, 2023). "According to these results, ISG15 deficiency may actually increase resistance to severe viral infections." (PMID 36146669, 2022). "The ISG15–/– mouse, in its turn, exhibited increased susceptibility to viral infection." (PMID 34675908, 2021). "ISG15 is an interferon-induced protein that has been implicated as a central player in the host antiviral response, and is the key element for the innate immune response against viral infection." (PMID 33918313, 2021). "For instance, ISG15 (ISG15 ubiquitin-like modifier) repressed interferon-α/β overamplification and autoinflammation, and the higher expression level of ISG15 in old pigs suggested that old females were more susceptible to viral infection." (PMID 31781648, 2019).
viral infection (continued). "Previous studies have shown that ISG15 is associated with chemotactic activity towards neutrophils, direction of ligated target proteins to intermediate filaments, cell-to-cell signaling, and antiviral activity during viral infections." (PMID 25238261, 2014). "It is attractive to speculate that the increased susceptibility of ISG15−/− mice to several virus infections, including herpesvirus and influenza virus, is mediated at least in part by a defect in macrophage phagocytosis." (PMID 24137104, 2013). "A slight diminution of the apoptosis induced by these compounds was detected in the absence of ISG15, indicating that, although it could be implicated in general apoptosis, ISG15 mainly regulates the apoptosis in response to viral infection." (PMID 24137104, 2013). "Furthermore, we identified a rare population in cluster 6, which expressed Ifi211, Isg15, and Trim30a; these genes are associated with defence against viral infection; however, their role in pulmonary fibrosis is unknown." (PMID 37771586, 2023). "Several IFN-stimulated genes, such as ISG15, have also been linked to the regulation of mitochondrial function during viral infection suggesting a secondary wave of mitochondrial reprogramming may occur following the TLR engagement and the induction of type I IFN responses." (PMID 31827178, 2019). "Its elevated levels in the serum of COVID-19 patients underscore a potential role for ISG15 in either combating or exacerbating viral diseases." (PMID 40719862, 2025). "Although ISG15 was identified as a strong predictor for distinguishing CHIKV‐infected from noninfected states, its widespread upregulation across various viral infections limits its specificity as a CHIKV‐specific diagnostic marker." (PMID 39764561, 2025). "As an IFN-stimulated gene (ISG), ISG15 is a key orchestrator of immune defense during viral infection and has already been described participating in the SARS-CoV-2 infection, inflammation, and immune responses." (PMID 40877796, 2025). "ISG15 can be conjugated to both host and viral proteins through a process known as ISGylation, which has been shown to restrict several viral infections." (PMID 39861921, 2025). "Interferon-stimulated gene 15 (ISG15) is an abundant interferon-stimulated gene known to have several roles in response to viral infections." (PMID 40778772, 2025). "Consistent with previous findings in the context of Human Immunodeficiency virus type 1 (HIV-1) vaccines, this study further supports the potential of ISG15 as an effective adjuvant for vaccines targeting viral infections such as ZIKV and SARS-CoV-2." (PMID 40733673, 2025). "Several ISGs, such as MxA, ISG15 and IFI27, exhibit unique expression patterns and robust diagnostic performance in identifying viral infections." (PMID 39861921, 2025). "The molecular mechanism controlling fetal inflammation identified in the present study is different from that of the well-established IFN/ISG15 axis in response to virus infection." (PMID 39589832, 2025). "Interferon-stimulated gene 15 (ISG15) is a ubiquitin-like protein and, as such, acts as a post-translational modifier that plays a critical role during bacterial and viral infections after interferon (IFN) production." (PMID 40631552, 2025). "The ubiquitin-like protein ISG15 is activated in response to type 1 interferons, and its conjugation to proteins regulates the response to bacterial and viral infection." (PMID 40436319, 2025). "ISG15‐deficient cells exhibited enhanced and prolonged ISG expression and a concomitant resistance to virus infection, a phenotype also associated with USP18 deficiency." (PMID 39931755, 2025). "For example, ISG15 is one of the most significantly induced genes in response to viral infection and was the first identified ubiquitin-like (UBL) protein induced by type I interferon." (PMID 41476985, 2025).
viral infection (continued). "First, we found a significant inhibitory effect of PRV on the expression of RACK1, IFN‐β, ISG15, and ISG20 in cells during the late phase of viral infection, indicating a potential association between RACK1, IFN‐I pathway, and PRV infection." (PMID 41395239, 2025). "Similar to viral infections, bacterial infections induce ISG15 expression, which can, in turn, influence bacterial survival and dissemination by either enhancing bacterial clearance or promoting the antibacterial immune response." (PMID 40103488, 2025). "Altogether, these experiments highlight the impact on viral infection of the C‐terminal di‐Gly motif of ISG15, via its regulation of IFN signalling." (PMID 39931755, 2025). "ISG15 has proinflammatory properties following viral infection, supporting the inflammatory profile found in vivo." (PMID 40143422, 2025). "Predominantly, C/I members (e.g. IFNs) exhibit low or abolish basal expression and acquire robust upregulation upon virus-infection; while a few execute enhanced basal levels followed by tremendous upregulation (e.g. ISG15)." (PMID 40131776, 2025). "In stark contrast, Isg15−/− mice exhibit high vulnerability to diverse viral infections, succumbing rapidly to viruses that wild-type mice resist." (PMID 41472304, 2025). "Ubiquitomics remains an understudied field in non-mammalian species, yet our results strongly suggest a key role of ubiquitin and ISG15 in the immune response of fish to viral infection." (PMID 41181121, 2025). "An alternative role for ISG15 during viral infection has been demonstrated in knockout mouse models." (PMID 40719862, 2025). "While also confirming DV inhibition of IFNAR signaling, our results further suggest that ISG15 function is targeted for successful viral infection." (PMID 38384473, 2024). "Morales and Lenschow (2013) reviewed the current understanding of ISG15, examining its role in mediating protection against different viral infections and exploring the mechanisms by which it exerts antiviral activity." (PMID 39282474, 2024). "The review also integrated new findings on individuals deficient in ISG15 and the identification of a cellular receptor for ISG15, providing deeper insights into how ISG15 influences the host response to viral infections." (PMID 39282474, 2024). "Deficiencies in MX1 and ISG15 and in genes of the OAS group have been associated with higher susceptibility to viral infections in mice." (PMID 38236818, 2024). "Protein modification by the ubiquitin-like protein ISG15 (ISGylation) plays a crucial role in the immunological defense against viral infection." (PMID 39512937, 2024). "Despite ISG15-knockout cells having full machinery to control viral infection as well as hyper-responsiveness to exogenous IFNα, they did not respond properly to DV infection." (PMID 38384473, 2024). "Their work highlights the importance of ISG15 in the immune system's response to viral threats, emphasizing its potential as a target for therapeutic interventions in viral diseases." (PMID 39282474, 2024). "ISG15 (Interferon stimulated gene 15) plays a key role in the innate immune response to viral infection via a process known as ISGylation upon activation by type I interferons or by viral/bacterial infections." (PMID 38902252, 2024). "Silencing cGAS resulted in a strong decrease in the Chlamydia-induced upregulation of ISG15, indicating that detection of nucleic acids was involved, such as in viral infection." (PMID 39345209, 2024). "The influence of extracellular ISG15 during viral infections should be further explored in the future." (PMID 38384473, 2024). "Perng and Lenschow (2018) focused their review on the multifaceted role of ISG15, a ubiquitin-like protein, in the host's response to viral infection." (PMID 39282474, 2024). "Originally, USP18 is identified as a deISGlase, which specifically cleaves the small ubiquitin-like ISG15 from ISGlated proteins to dampen the interferon-induced overwhelmed response to viral infections." (PMID 38779488, 2024).